NNMT (nicotinamide N-methyltransferase)
Diseases named in the same sentence as NNMT in open-access papers (continued):
Sharing a sentence is not in itself a finding about the gene and the disease.
cancer (continued). "The identification of such compounds, able to selectively and effectively inhibit enzyme activity, will also contribute to disclose mechanisms of action of NNMT within cancer cells and open new perspectives for therapeutic strategy development." (PMID 36139012, 2022). "We found that NNMT expression was significantly higher in MSI subtype than in MSS subtype cancers (p = 0.0045)." (PMID 35177765, 2022). "Further analysis identified a differentially methylated region (DMR) within the NNMT promoter, which is hyper‐methylated in the sensitive cancer cells." (PMID 36382559, 2022). "Here we show that nicotinamide-N-methyltransferase (NNMT) is a host factor that mediates metabolic dysfunction in the livers of cancer-bearing mice." (PMID 35705545, 2022). "The metabolic enzyme nicotinamide‐N‐methyltransferase (NNMT) is highly expressed in various cancer entities, suggesting tumour‐promoting functions." (PMID 35678045, 2022). "Previous studies indicated that dysregulated expression of nicotinamide N-methyltransferase (NNMT) contributed to the tumor progression and predicted poor prognosis in various cancers." (PMID 35233465, 2022). "To extend the findings of NNMT inhibition on cancer cells from 2D to more physiological 3D tumour models, we used patient‐derived ex vivo ALI models of three different ccRCC tumours." (PMID 35678045, 2022). "NNMT is known to impair the methylation potential of cancer cells by exhausting methyl units from S-adenosyl methionine to form the stable metabolic product 1-methylnicotinamide." (PMID 35276059, 2022). "Comparison of different cancer stages suggests that the fraction of patients with stromal NNMT overexpression increases as early-stage tumors advance from stage I to stage II." (PMID 35177765, 2022). "In late-stage cancer cases, NNMT overexpression was found in 19/77 (24.7%) stage III and 1/30 (3.3%) stage IV patients." (PMID 35177765, 2022). "Recent studies showed that NNMT is aberrantly expressed in several cancers and played an important role in cancer cell adhesion, invasion, and metastasis." (PMID 35387964, 2022). "In this study, we found expression of NNMT negatively associates with OXPHOS gene expression and cancer cell sensitivity to OXPHOS inhibition." (PMID 36382559, 2022). "In ccRCC, NNMT protein was higher in tumor tissue and ectopic expression of NNMT promoted cancer cell proliferation." (PMID 36313638, 2022). "Previous studies suggested that glucose metabolism closely correlated with the drug resistance of cancer cells, and NNMT has emerged as a regulator of cancer energy metabolism." (PMID 35387964, 2022). "In order to understand changes of NNMT protein expression in cancers, we first examined normal colonic and rectal mucosa by immunohistochemistry." (PMID 35177765, 2022). "Reportedly, NNMT was up-regulated in the livers of tumor-bearing mice and was implicated in the down-regulation of the urea cycle and uracil production, which may be involved in the process of protein breakdown and amino acid buildup in cancer cells that promotes tumor cell proliferation." (PMID 36386816, 2022). "The reduced sensitivity to OXPHOS inhibition of cancer cells upon NNMT overexpression and DNMT1 knockdown was also reflected by attenuated ATF4 upregulation and p‐S6 downregulation when treated with OXPHOS inhibitors (Gboxin, Oligomycin A, and Berberine)." (PMID 36382559, 2022). "This review provides a comprehensive understanding of recent advances on NNMT functions in different tumors and deciphers the complex roles of NNMT in cancer progression." (PMID 35338115, 2022). "The STAT3 phosphatase inhibitor STATTIC inhibited the cancer-promoting effect of NNMT overexpression on colony formation and migration in transwell experiments." (PMID 35851575, 2022). "Taken together, these data thus suggest that low NNMT expression leads to increased SAM levels in OXPHOS inhibition‐sensitive cancer cells compared with that in resistant cancer cells." (PMID 36382559, 2022).
cancer (continued). "In contrast, late-stage cancers displayed NNMT overexpression significantly more frequently (p = 0.0055) in older patients (62.5%) than in younger patients (21.7%)." (PMID 35177765, 2022). "Immunohistochemical examination of 679 patients illustrates that NNMT protein is predominantly expressed in the cancer stroma at varying levels, and about 20% of cancer tissues overexpress NNMT when compared to levels observed in normal colorectal mucosa." (PMID 35177765, 2022). "In conclusion, our first pan-cancer investigation of NNMT demonstrated differential NNMT expression between tumors and normal tissues, as well as a link between NNMT expression and clinical prognosis and DNA methylation." (PMID 36386816, 2022). "NNMT inhibition impairs ccRCC metabolism alone or in combination with other agents and drives primary and metastatic cancer cells into cell death." (PMID 35678045, 2022). "However, in the last decades, a great number of studies reporting NNMT upregulation in association with cancer have been published, thus evidencing an increasing interest in the speculating function exerted by the enzyme in the context of malignant transformation." (PMID 36139012, 2022). "Together, these results suggest an important role of the liver NNMT pathway in cancer cachexia at the multi-organ level." (PMID 35705545, 2022). "In another study, NNMT was reported to influence the methylation of tumour suppressors and oncogenes directly, thereby supporting cancer cell survival." (PMID 35678045, 2022). "This study not only unravels the roles of NNMT in cancer-induced host pathophysiology but also offers a basis to study the complex systemic syndrome that severely impacts patients with incurable cancers." (PMID 35705545, 2022). "In early-stage cancer cases, NNMT overexpression was found in 25/211 (11.8%) stage I and 90/361 (24.9%) stage II patients (p = 0.0001)." (PMID 35177765, 2022). "We also examined NNMT mRNA expression levels in a variety of cancer cell lines from the cancer cell line encyclopedia." (PMID 35177765, 2022). "Inappropriately high expression and activity of NNMT, commonly present in various types of cancer, has the potential to disrupt NAD+ homeostasis and cellular methylation potential." (PMID 34073600, 2021). "Many of these inhibitors have yet to be tested in in vitro cancer models systems, and questions remain about their selectivity towards NNMT in relation to other methyltransferases as well as their cell permeability." (PMID 34680055, 2021). "There is a growing body of evidence which suggests that NNMT regulates the expression of pro-oncogenic genes in cancer via the regulation of intracellular SAM concentrations." (PMID 34680055, 2021). "For almost twenty years, NNMT has been described to be upregulated in several solid cancers, participating in crucial mechanisms leading to cancer progression, metastasis and resistance to chemo- and radiotherapy." (PMID 34439880, 2021). "NNMT is currently the focus of intense drug discovery studies for developing NNMT inhibitors as anti-cancer therapeutics." (PMID 33387303, 2021). "It has been suggested that a metabolic switch towards glycolysis (cancer-characteristic Warburg effect) in primed hESCs depends on the drop in NNMT activity." (PMID 34073600, 2021). "In this review, we discuss the evidence supporting a role for NNMT in the progression of the cancer phenotype and how it achieves this by driving the activity of pro-oncogenic NAD+-consuming enzymes." (PMID 34680055, 2021). "Some studies reported the occasional presence of nuclear staining of NNMT both in normal and cancer tissues, although NNMT is described to be a cytoplasmic protein." (PMID 34827592, 2021). "Previous studies have indicated that NNMT is a master regulator in cancer cell metabolism in general and Warburg effect in particular." (PMID 33446144, 2021).
cancer (continued). "Transcription factors STAT3 and hepatocyte nuclear factor 1 β (HNF1 β) have been documented to increase NNMT promoter activity in cancer cells, but, beyond that, its transcriptional regulation has, for long time, remained rather unexplored." (PMID 34073600, 2021). "The intervening 20 years have seen a rapid increase in interest in the role of NNMT in cancer, fuelled by the increasing knowledge of its involvement in the many cellular pathways essential to both tumour and non-tumour survival." (PMID 34680055, 2021). "Despite the widely recognised importance of NNMT overexpression in cancer, few studies have investigated how NNMT expression is regulated." (PMID 34680055, 2021). "A negative correlation was observed between the expression levels of miR-449a and nicotinamide N-methyltransferase (NNMT), a metabolic enzyme linked to cancer, in EGFR-TKI-resistant NSCLC models." (PMID 34830377, 2021). "The presence of several STAT3, and a single HNF-1β TFBS in the NNMT promoter region suggest a mechanism for the observed induction of NNMT expression in cancer." (PMID 34680055, 2021). "Recently, NNMT was found to be overexpressed in stroma of CRC 24 and cancer associated fibroblasts of gastric carcinoma 25 by immunohistochemical analysis of clinical samples." (PMID 34539890, 2021). "Using this approach, inhibitors with low EC50 values have been successfully developed, some of which demonstrate efficacy in in vitro cancer models and increased specificity towards NNMT." (PMID 34680055, 2021). "NNMT has been found highly expressed in a wide variety of cancers, and NNMT over-expression can enhance the aggressiveness of various cancers, including CRC." (PMID 34572508, 2021). "Cancer cells appear to have taken advantage of the NNMT/NAMPT pathway to promote the neoplastic phenotype by increasing the activity of NAD+-dependent processes such as sirtuins and PARP-1." (PMID 34680055, 2021). "Elevated NNMT expression is a feature of numerous cancers in which it plays a central role in inducing cancer metastasis along with changes in cell biochemistry and cellular signalling which are of significant survival benefit to the tumour cell." (PMID 33387303, 2021). "Here, we review the role of NNMT in cancer, with respect to its involvement in dynamic process of transition from tumor-suppressive state of cellular senescence to stem cell-like phenotypic state, related to the acquisition of therapy resistance." (PMID 34073600, 2021). "Its expression in several cancer cell lines has been widely discussed in the literature, and recent work established a link between NNMT expression and metabolic diseases." (PMID 33668468, 2021). "Functional studies revealed that knockdown of NNMT expression resulted in reduced migration and invasion of various cancer cells, suggesting an pro-metastatic role of NNMT." (PMID 33446144, 2021). "The sources of critical NAM elevation in cancer cells, which would activate NNMT to the extent that would restrict the availability of SAM for other cellular methylation reactions, have not been defined." (PMID 34073600, 2021). "One of the metabolic enzymes, NNMT, is often over-expressed in various types of cancer, where it regulates NAD+ consumption-recycling flux and cellular methylation potential." (PMID 34073600, 2021). "In the light of this evidence, it is reasonable to attribute to NNMT a promising role as a potential biomarker for the diagnosis and prognosis of urologic neoplasms, as well as a molecular target for effective anti-cancer treatment." (PMID 34439880, 2021). "In this review, increased NNMT expression in cancer cells replicates all these effects, demonstrating the central importance of NNMT expression to the EMT." (PMID 34680055, 2021). "The increase in MNAM level has been, however, observed in various cancer cell lines and cancer types, in which NNMT expression was likewise elevated, but the source of NAM was not explored." (PMID 34073600, 2021).
cancer (continued). "Nicotinamide n‐methyltransferase (NNMT) has good biochemical activity and epigenetic regulation, and has been reported as a major metabolic regulator of cancer." (PMID 31989785, 2020). "Nicotinamide N-methyltransferase (NNMT) is highly expressed in several cancers and can regulate cell epigenetic status and various cell metabolism pathways, such as ATP synthesis and cellular stress response." (PMID 32489327, 2020). "Recently, it was reported that aggressive cancer cell lines have higher levels of 1-MNA because of increased NNMT activity." (PMID 36703437, 2020). "Although elevated expression of NNMT has been reported in several cancers, NNMT expression was prominent in RCC." (PMID 32992891, 2020). "Previous studies have shown that NNMT is a potential marker in some cancers, few studies have focused on the biological role of NNMT." (PMID 33193702, 2020). "NNMT has been recently reported to participate in the development and progression of various carcinomas and regulate cancer metabolism." (PMID 32489327, 2020). "In the cancer cells which rely on STAT3-mediated increase of NNMT expression, this can be of the utmost importance." (PMID 33182817, 2020). "NNMT is important for cancer cell migration, invasion, and proliferation, and is overexpressed in a variety of cancers, including lung, liver, bladder, and colon." (PMID 32824193, 2020). "In recent years, role of NNMT has been expanded beyond excess vitamin B3 clearance as it involves in regulation of multiple metabolic pathways in adipose, liver, and cancer cells through consuming and generating active metabolites." (PMID 33193702, 2020). "The progressive increase in NNMT expression from benign endometria to primary EC and finally metastatic EC suggests that NNMT plays a role in cancer development and metastasis." (PMID 31652035, 2019). "NNMT is a metabolic protein shown to be involved in cancer dissemination, treatment failure, and recurrence." (PMID 31652035, 2019). "Increased phospho-Akt (pAkt) levels in response to NNMT overexpression have been reported in in vitro studies of different cancer types." (PMID 31652035, 2019). "In 1984, Seifert R was the first to confirm that alterations in NNMT activity are involved in the development and progression of carcinoma in vivo." (PMID 31101119, 2019). "NNMT is a special metabolic enzyme, which exerts specific control over cells methylation potential thereby broadly impacting the epigenetic state of cancer cells." (PMID 29875994, 2018). "For instance, it has been shown that the metabolic enzyme nicotinamide N-methyltransferase (NNMT) is overexpressed in a variety of human cancers." (PMID 29875994, 2018). "NNMT has also been reported to be overexpressed in a variety of human cancers and to promote epigenetic remodeling in cancer by consuming methyl units from S-adenosyl methionine (SAM), resulting in a metabolic sink." (PMID 29228658, 2017). "In view of these data, it appears that the effect of NNMT overexpression and downregulation is tissue and cancer specific." (PMID 28102366, 2017). "Previous studies also showed that NNMT expression is elevated in “aggressive” cancer cell lines and NNMT has a role in regulation of cellular migration." (PMID 28412735, 2017). "Our results show that NNMT protein expression is detectable both in the carcinoma and adjacent stroma, with NNMT expression in some specimens exclusively present only in one of the compartments." (PMID 28412735, 2017). "The results of nude mice tumorigenesis experiments on Bcap-37 also showed that down-regulation of NNMT expression inhibited cancer cells tumorigenicity in vivo." (PMID 24558488, 2014). "Proteomics analysis and DNA microarray analysis showed that NNMT was expressed at markedly higher levels in several kinds of cancers." (PMID 24558488, 2014).
cancer (continued). "Although abnormal NNMT expression has been identified in several types of tumors, the biological significance of alterations in NNMT activity in pathological conditions remains poorly understood, and the role of NNMT in cancer cell metabolism is still unclear." (PMID 23990942, 2013). "NNMT was detected in all cancer cell lines tested, showing a very high expression level in PE/CA-PJ15 cells." (PMID 23990942, 2013). "In fact, in athymic mice, NNMT silencing induced a marked reduction in tumor volume, suggesting the involvement of the enzyme in cancer development." (PMID 23990942, 2013). "NNMT mRNA was detected in all of the cancer cell lines tested, as its expression level was very high in PE/CA-PJ15 cells." (PMID 23990942, 2013). "Authors hypothesize that depletion of SAMe is due to NNMT overexpression and overutilization of the methyl donor, which has been also observed in many cancers, including lung." (PMID 39941901, 2025). "Targeting NNMT might prove to be a promising therapeutic strategy to influence the cancer epigenome for treatment advantages." (PMID 40650308, 2025). "It has also been hypothesized that elevated levels of NNMT may promote cancer radioresistance by removing the inhibitory block of nicotinamide upon PARP-1, thereby enhancing DNA repair." (PMID 40497995, 2025). "The phenotypic impact of the small molecule NNMT inhibitors on cancer cells was established by assessing the viability of OS and MCC cell lines by means of the MTT assay at different timepoints (0 h, 24 h, 48 h and 72 h) following treatment with the NNMT inhibitors." (PMID 41301471, 2025). "NNMT expression reduces sensitivity to anticancer drugs in several cancer cell types." (PMID 40853419, 2025). "Moreover, NNMT inhibition has shown potential in sensitizing cancer cells to chemotherapy and radiotherapy." (PMID 40864763, 2025). "In other cancer types, including adrenocortical carcinoma, cholangiocarcinoma, kidney chromophobe, pheochromocytoma and paraganglioma, thyroid carcinoma and skin cutaneous melanoma, NNMT expression appears to be significantly lower." (PMID 39941901, 2025). "Notably, NNMT’s impact on NAD+ depletion and methionine cycle dysregulation is a shared hallmark in cancers such as HCC and ovarian tumors; yet, its functional outcomes diverge depending on cellular context." (PMID 40427612, 2025). "This suggests that NNMT upregulation may be a critical factor contributing to tumor progression in these cancers, potentially enhancing tumorigenic processes such as cell proliferation, migration, and chemoresistance." (PMID 39941901, 2025). "High levels of NNMT expression have also been reported at both mRNA and protein levels in Merkel cell carcinoma and ovarian cancer as a poor prognostic feature and an advantage for cancer progression." (PMID 39941901, 2025). "In addition to the function of NNMT expressed in cancer cells, NNMT in stromal cells also plays a crucial role in cancer." (PMID 39887931, 2025). "NNMT inhibitors may be used in the future to increase drug sensitivity in paclitaxel-resistant cancers." (PMID 40853419, 2025). "Firstly, NNMT reduces methylation potential in cancer cells by altering the SAM:SAH ratio." (PMID 40497995, 2025). "Moreover, MNA has been reported to inhibit the generation of reactive oxygen species and NNMT has been reported to be upregulated in cancer cells and is generally thought to promote cell proliferation and migration." (PMID 41159029, 2025). "Therefore, NNMT plays a crucial indicator in cancer progression and offers potential as an effective target for anticancer treatment." (PMID 39399490, 2024). "The cancer expression of KMTs such as NSD1 is linked to SAM availability and is inversely correlated to the activity of nicotinamide-N-methyltransferase (NNMT), whose product, 1-methyl nicotinamide, is a methyl sink for an excess of methyl groups, carried by the methyl donor SAM." (PMID 39280246, 2024).